SNORA15B-2 (small nucleolar RNA, H/ACA box 15B-2)
Synonyms: SNORA15C
Gene: Small nucleolar RNA gene on chromosome 7 (65,760,052 to 65,760,186, forward strand). Ensembl gene ENSG00000206785.
Gene Ontology:
Biological process: RNA processing
Cellular component: nucleolus
Homologues: Orthologues: mouse Snora15 (83% identical), rat LOC120096108 (81% identical). Paralogues in human: SNORA15B-1 (100% identical), SNORA15 (97% identical).